MEG3 (maternally expressed 3)
Diseases named in the same sentence as MEG3 in open-access papers (continued):
Sharing a sentence is not in itself a finding about the gene and the disease.
tumor (continued). "On the other hand, when MEG3 was overexpressed, the average xenograft tumor appearance time was significantly increased compared to the corresponding control group (16.18 ± 4.02 days versus 9.4 ± 2.37 days, n = 6, P = 0.003787 <0.01)." (PMID 29449541, 2018). "The overexpression of MEG3 in MDA-MB-231 cells suppressed xenograft tumor growth and angiogenesis, and reduced P-AKT, PCNA, and MMP-9 protein expression in the tumors formed in the mice." (PMID 30545127, 2018). "Maternally expressed gene 3 (MEG3) is a maternally imprinted lncRNA with a tumor suppressor role in various tumors." (PMID 29596364, 2018). "And qRT-PCR assays showed that the MEG3 levels in tumor tissues from the LV-MEG3 group were higher than those in tumors from the LV-NC group." (PMID 30282996, 2018). "Murine Meg3 was proposed to possess tumor suppressor properties and extensive studies have been conducted recently to explore the mechanisms on how Meg3 inhibits cell growth." (PMID 29690867, 2018). "MEG3 dysregulation was studied in xenograft models (established by subcutaneous implantation), and tumor growth was compared." (PMID 29596364, 2018). "Of the tumor-suppressive lncRNAs, MEG3 correlated with stage, tumor invasion depth, and tumor size, whereas expression of GAS5 correlated with prognosis." (PMID 30518158, 2018). "Several lines of evidence suggest that increased methylation of the MEG3 ICR, regulating a known tumor suppressor, is associated with decreased expression of MEG3, albeit with increased expression of the reciprocally imprinted DLK1 gene." (PMID 30246009, 2018). "The lncRNA GAS5 was significantly down-regulated in NSCLC tissues and cell lines; MEG3, which was identified to be up-regulated and played as a tumor suppressor gene in a lot of tumors." (PMID 29899163, 2018). "As a tumour suppressor, MEG3 inhibits tumour cell proliferation possibly through the induction of apoptosis." (PMID 29416011, 2018). "For example, the tumor suppressor MEG3 introduced into HCC tumor through a novel delivery system effectively induced apoptosis in HCC cells, presenting a potential lncRNA-targeted therapy with fewer side effects." (PMID 30105249, 2018). "In contrast, hypermethylation of MEG3 DMR sites outside a CTCF binding domain is associated with decreased miRNA expression and decreased tumor aggressiveness." (PMID 28506242, 2017). "Long non-coding RNA MEG3 is a newly found tumor suppressor and plays a very important role in the regulation of a variety of tumor formation and progression." (PMID 29029424, 2017). "lncRNA MEG3, a newly discovered lncRNA with tumor suppressor function, plays an important role in the formation and progression of many tumors." (PMID 29029424, 2017). "The inhibition effect of MEG3 on tumor cells proliferation was tested in several cancer cell lines with a number of independent assays, including colony formation, growth curve and BrdU incorporation." (PMID 29348851, 2017). "The loss of this RNA expression causes cell growth and proliferation in human cancers, thus supporting the claim that Meg3 is a tumor suppressor lncRNA." (PMID 29206174, 2017). "Meanwhile, overexpression of MEG3 can inhibit the proliferation of tumor cell lines, which indicates that it plays a role of tumor suppressor genes." (PMID 28157702, 2017). "MEG3 is a maternally expressed imprinted gene that acts as a tumor suppressor gene in a number of malignancies." (PMID 28321286, 2017). "One of many maternally imprinted lncRNAs, MEG3 exhibits the hallmarks of a tumor suppressor, namely inhibition of proliferation and induction of apoptosis in numerous cancers." (PMID 29113413, 2017).
tumor (continued). "Specifically, expression patterns of a large subset of the 14q32 miRNAs were associated with methylation patterns in the MEG3 DMR region, and both were associated with tumor aggressiveness." (PMID 28506242, 2017). "These transcripts are annotated as MEG3 (Maternally Expressed 3) which is a maternally imprinted gene with all spliced transcripts annotated as lncRNAs and is a well-known lncRNA tumor suppressor." (PMID 28611953, 2017). "Some exhibit hallmarks of tumor suppression, such as MEG3, while others, such as HOTAIR, behave as oncogenes through increased proliferation and reduced survival." (PMID 29113413, 2017). "Maternally expressed gene 3 (MEG3) is the first lncRNA to be found to have tumor suppressor function, which is expressed in many human normal tissues." (PMID 28157702, 2017). "The tumour-suppressing long non-coding RNA (lncRNA) MEG3 and microRNAs (miRNAs) miR-329 and miR-410 have been reported to be downregulated in oral squamous cell carcinoma resulting in upregulation of Wnt-7b and β-catenin signalling." (PMID 28149533, 2017). "Maternally Expressed Gene 3 (MEG3), a tumor suppressor, is involved in the development and progression of many cancers." (PMID 27802187, 2017). "Previous studies have showed that MEG3 was expressed in brain, pituitary, ovary and other normal tissues, while the expression was reduced or even lost in a variety of tumor cell lines." (PMID 28157702, 2017). "Lower expression of MEG3 is significantly correlated with low histological grade, deep tumor invasion, and advanced TNM stage." (PMID 28108736, 2017). "Using this approach with different cancer types, oncogenic lncRNAs such as MALAT-1, ANRIL, UCA1, and tumor suppressor lncRNAs like Gas-5 and MEG3 have been functionally characterized." (PMID 28715488, 2017). "In various tumor tissues, the expression of MEG3 decreased significantly in brain, bladder, breast, cervical, colon, bone marrow, liver, lung and prostate cancer cells in the expression decreased obviously." (PMID 29029424, 2017). "For example, maternally expressed 3 (MEG3) is a maternally expressed, imprinted lncRNA gene that acts as a growth suppressor in tumor cells." (PMID 28425476, 2017). "Restoring proper MEG3 expression level inhibits tumor cell proliferation and induces tumor cell apoptosis as well as autophagy." (PMID 29069869, 2017). "Considering that HOTAIR oncogenic activity is seen in multiple cancers and MEG3 tumor suppressor activity is also observed across cancers, the simple explanation of differing mechanisms in differing tumors does not seem applicable." (PMID 29113413, 2017). "Overexpression of MEG3 gene can inhibit the proliferation of tumor cell lines and act as a tumor suppressor gene." (PMID 29029424, 2017).
tumor (continued). "MEG3 is an imprinted gene belonging to the DLK1-MEG3 locus located on chromosome 14q32.3 which is the first lncRNA to be found with tumor suppressor function." (PMID 28157702, 2017). "The effects of MEG3 expression on cancer development are well-documented and MEG3 has been attributed as a tumor suppressor based on its involvement in tumor development." (PMID 29069869, 2017). "MEG3 is expressed in normal tissues but is either lost or decreased in many human tumors and tumor derived cell lines." (PMID 29069869, 2017). "In contrast, the MEG3 rs10132552 CT genotype had a better response to treatments for the primary tumour compared with the TT genotype (OR = 0.261, 95%CI = 0.089–0.770, P = 0.015)." (PMID 28814798, 2017). "As predicted, the expression levels of MEG3 in tumor tissues of the U937-MEG3-OE group were significantly higher than those of the control group." (PMID 28400619, 2017). "For example, studies have shown that restoring the expression of MEG3 suppresses tumor growth in nude mice." (PMID 29069869, 2017). "Further in vivo observations confirmed that re-expression of MEG3 in PDFS cells can reduce tumor growth in nude mice." (PMID 29348851, 2017). "Some lncRNAs, such as HOTAIR, H19, NEAT1, HNF1A-AS, ANRIL, are reported to be oncogenic molecules in NPC, while GAS and MEG3 lncRNAs act as tumor suppressors." (PMID 28467811, 2017). "Based on findings described in literatures, MEG3 is an RNA-based tumor suppressor and is involved in the etiology, progression, and chemosensitivity of cancers." (PMID 29069869, 2017). "In order to further reveal the role of MEG3 demethylation in the tumor suppression effect of 5-Aza-CdR, we designed the experiments in below." (PMID 29287592, 2017). "It means MEG3 methylation can be a candidate of plasma biomarker for prognosis and is valuable in detection of tumor recurrence." (PMID 29287592, 2017). "The loss of MEG3 expression promotes tumor progression through specific molecular mechanisms, and re-expression of MEG3 in tumor cells inhibits proliferation and induces apoptosis." (PMID 27802187, 2017). "Re-expression of MEG3 inhibits proliferation, induces apoptosis, and inhibits the anchorage-independent growth of human tumor cells." (PMID 27043545, 2016). "Univariate analysis using the Cox proportional hazard regression model revealed a statistically significant correlation between RFS of NMIBC and MEG3 level (p = 0.033), and tumor stage (p = 0.030)." (PMID 27793008, 2016). "Although the regulation of MEG3 and its precise mechanism of action in cancer are still well known, emerging evidence strongly demonstrates that MEG3 functions as a novel lncRNA tumor suppressor." (PMID 26934323, 2016). "Multivariate analysis including MEG3 and tumor stage showed that MEG3 (p = 0.046) and tumor stage (p = 0.041) were independent prognostic factors for the RFS of NMIBC." (PMID 27793008, 2016). "To investigate GE11-VLPs-MEG3 inhibition of tumor growth in vivo, we constructed a nude mouse model of HCC." (PMID 26992211, 2016).
tumor (continued). "An association between lncRNAs and the immune response has only recently emerged, and only a few have been shown to be expressed in endothelial cells, and adipocytes, with preferential expression of MEG3 and H19 observed in tumour stroma." (PMID 27685983, 2016). "Specifically, the lncRNA maternally expressed gene 3 (MEG3) has been shown to function as a tumor suppressor and inhibit cell proliferation in a number of human cancer cell lines." (PMID 27832204, 2016). "Our previous studies also revealed that lncRNA ANRIL and MVIH function as oncogenes in NSCLC cells, while MEG3 exerts tumor-suppressive function." (PMID 26840083, 2016). "All presently available studies report that insertion of MEG3 cDNA into plasmids coupled with liposome-mediated cell transfection is the only method to realize tumor inhibition." (PMID 26992211, 2016). "To further examine the influence of MEG3 on clonogenic survival of tumor cells, we performed a colony formation assay on soft agar." (PMID 26992211, 2016). "Intriguingly, the promoter-associated CpG island of MEG3 was found frequently hypermethylated in both solid and hematological malignancies, indicating that methylation-mediated silencing may serve as an alternative mechanism for inactivation of tumor suppressive lncRNAs." (PMID 27689399, 2016). "Maternally-expressed gene 3 (MEG3), an imprinted gene located on chromosome 14q32, is considered to act as a tumor suppressor lncRNA." (PMID 27043545, 2016). "Levels of MEG3 mRNA in tumor tissues from the GE11-VLPs-MEG3 group were higher than in the control groups." (PMID 26992211, 2016). "Included in this list was the maternally expressed 3 gene (MEG3), one of the few lncRNAs known to be preferentially expressed in tumour stroma." (PMID 27685983, 2016). "We then integratedgene expression data from 17 published studies, representing 2,999 primarybreast tumours, and found that MEG3 had the lowest average expression andwidest range of expression in the aggressive and difficult-to-treat basalmolecular subtype." (PMID 26205790, 2015). "MEG3 is known to be down-regulated in multiple cancers and tumour cell proliferation is inhibited by MEG3 expression." (PMID 26537449, 2015). "MEG3 is abundantly expressed in normal human tissues and its expression is often lost in cancer, suggesting that it functions as a tumor suppressor lncRNA." (PMID 26064090, 2015). "Ectopic expression of MEG3 in nude mice confirmed the tumor suppressive nature of this lncRNA, since MEG3 upregulation resulted in inhibition of CRC proliferation." (PMID 26064090, 2015). "Our research confirms for the first time that, as a tumor suppressor, MEG3 improves LAD chemosensitivity, and shows that it has potential to be used as a therapeutic target to reverse the cisplatin resistance of LAD patients." (PMID 25992654, 2015). "We next used qRT-PCR to investigate the MEG3 expression of tumor tissues from 41 patients with advanced LAD treated with cisplatin-based chemotherapy." (PMID 25992654, 2015).
tumor (continued). "In this study, we have identified that ectopic expression of MEG3 gene in human tumor cells significantly inhibits proliferation and induces apoptosis." (PMID 26444285, 2015). "MEG3 was reported as a tumor suppressor, its expression was decreased in NSCLC tumor tissues and associated with poor prognosis." (PMID 26159226, 2015). "In culture and colony formation, the re-activation of MEG3 expression inhibits tumor cell proliferation." (PMID 25663854, 2015). "Among them, 35 cases (70 %) showed significantly reduced level of MEG3 in tumor tissues compared with their normal tissues, whereas only 8 cases (16 %) showed up-regulated MEG3 level in GC." (PMID 26253106, 2015). "We also observed thatTGFB2, TGFBR1 and SMAD2 genes had greater expressionin tumours with low MEG3 expression, further supporting our invitro cell culture results that MEG3 negatively regulates theTGF-β pathway genes." (PMID 26205790, 2015). "qRT-PCR analysis of MEG3 expression found it to be significantly higher in tumor tissues formed from pCDNA-MEG3-transfected A549/DDP cells than those from controls." (PMID 25992654, 2015). "MEG3 expression is lost in human gonadotroph-derived pituitary adenomas and most human tumor cell lines." (PMID 24757675, 2014). "For example, maternally expressed gene 3 (MEG3), a tumor suppressor non-coding RNA, was highly methylated at its promoter region in EAC." (PMID 25286960, 2014). "Of note, MEG3 was recently suggested to play a significant role as a novel tumor suppressor lncRNA in several human cancers and evidence of its association with tumorigenesis is growing every day." (PMID 25033876, 2014). "MEG3 is expressed in many normal tissues including breast, colon, liver, ovary but its expression is lost in many tumour cells." (PMID 24926662, 2014). "For example, expression of the non-coding, maternally expressed gene Meg3 has been shown to be lost in many kinds of primary human tumors and tumor cell lines." (PMID 25005035, 2014). "The long noncoding RNA MEG3 was reported to act as a tumor suppressor, too, but in a more consistent manner." (PMID 25741387, 2014). "miR-29 can regulate expression of MEG3, a tumor suppressive lncRNA, and miR-29 expression was down regulated in human HCC cells." (PMID 24926435, 2014). "One target of these changes is evidently MEG3, which emerges as a tumor suppressor in many different tissues." (PMID 25741387, 2014). "Several of the detected differentially expressed lncRNAs were well described members of cancer-related pathways, including tumor suppressors and oncogenes (e.g. MEG3, Xist, MALAT1, H19, GAS5, and HOTAIR)." (PMID 25264628, 2014). "Given their known functions and the findings in other cancers, DLK1 and MEG3 are good tumor-suppressor candidates." (PMID 25741387, 2014). "The results showed that the levels of MEG3 expression in tumor tissues formed from pCDNA-MEG3 cells were higher than those of tumors formed in control group." (PMID 24098911, 2013). "Inactivation of MEG3 in the brain increases the expression of genes involved in angiogenesis, suggesting that the tumour suppressor function of MEG3 works, in part, by inhibiting angiogenesis." (PMID 23887658, 2013). "Specifically, MEG3 expression was found to be significantly lower at later stages of tumor development and in tumors that had undergone increase in size." (PMID 24098911, 2013).